AR (androgen receptor)
Diseases named in the same sentence as AR in open-access papers (continued):
Sharing a sentence is not in itself a finding about the gene and the disease.
tumor (continued). "This predicted arrangement might suffer in the nucleus specific post-transcriptional processing during tumor development, exporting smaller folded base-paired fragments to the cytoplasm that may modulate other genes, including the androgen receptor signaling pathway." (PMID 26174796, 2015). "In addition to overexpressing AR, there is evidence that the maintenance of androgens within the tumor microenvironment may also be an important means by which canonical AR signaling drives castrate-resistant growth." (PMID 26566796, 2015). "Interestingly, we have identified one tumor sample where AR levels were unchanged which could be correlated with wild-type levels of active and total Notch." (PMID 25592291, 2015). "Since it has been shown that direct up-regulation of cyclinD1 expression by p52 leads to the proliferation of tumor cells, we propose that the cyclinD1 repression by AR/p52-02 may be due to the reduction of translocation of p52 to the nucleus that we show in the present study." (PMID 26622945, 2015). "We also examined expressed AR Isoforms AR-001, AR-002, AR-003, AR-004 (AR-V7), AR-005 and AR-201 to determine if differential expression of any of these isoforms might underpin the androgen insensitive phenotype in either our cell lines or the human tumours." (PMID 26553226, 2015). "However, several mechanisms, synthesis of endogenous androgen, AR mutations and induction of AR splice isoforms, and others, makes tumor independent of presence of external androgens, and this leads to treatment failure." (PMID 26491211, 2015). "A lesion, which is neoplasm or reactive hyperplasia, may be determined by clonality assay based on X-chromosome inactivation mosaicism and polymorphism at the phosphoglycerate kinase (PGK) and androgen receptor (AR) loci in female somatic cells." (PMID 24498024, 2014). "Thus, our working hypothesis is that dual targeting of PI3K and AR will provide a synergistic anti-tumor effect." (PMID 25103565, 2014). "Furthermore some results of in vitro investigations suggested that AR may displace ER and PR as a driver of tumor proliferation and growth in TNBC cell lines." (PMID 24978437, 2014). "However, during PCa development, integrin α6β1 becomes co-expressed with AR in the tumor cells." (PMID 25566502, 2014). "The lack of AR expression has been associated with increased invasive properties, suggesting that therapies able to restore its expression receptor may reduce tumor dissemination." (PMID 24797896, 2014). "Again, by activating PI3-K at low androgen concentration, stromal AR may act in concert with NF-kappa-B to induce the release of macrophage inflammatory protein-1 beta (MIP-1beta) in tumor microenvironment, or it may activate IKK-alpha-dependent gene transcription." (PMID 25646090, 2014). "Based on the results of this study, the ultrasound-destructible nanobubbles carrying AR siRNA that we prepared could not only enhance the imaging effect of transplanted tumor, but also distribute more widely in the tumor, compared with the control microbubbles - SonoVue." (PMID 24798477, 2014). "Moreover, tumor cells generally express a luminal phenotype driven by AR." (PMID 24199173, 2013). "However, our results raise the question whether AR, as assessed by IHC, is a good marker to define this tumor subgroup." (PMID 23663520, 2013). "Thus, even tumor cells are forced to balance signals to keep AR active." (PMID 24199173, 2013). "Interestingly, AR loss did not result in an increase in the percentage of tumor-bearing mice in the MARKO group compared to controls." (PMID 23593223, 2013). "We are also aware that expression levels not necessarily reflect biological activities and our hypothesis that tumor expression pattern of steroidogenic AKR1C3 and constitutively active AR variants would predict response to 2nd line therapies of CRPC needs to be tested upfront in clinical studies." (PMID 24244276, 2013). "This antagonism of AR may also contribute to the anti-tumor effects." (PMID 23880851, 2013).
tumor (continued). "Thus, the AR is considered to be a potential tumor suppressor for ER-positive breast cancer." (PMID 24403250, 2013). "Interestingly, factor analysis performed in the subgroup of 17 patients with Triple-negative tumours (data not shown), revealed strong association of p16 expression with Ki67 and their strong inverse relation to AR (but not ER or PR) expression." (PMID 22424533, 2012). "We also found that AR positivity was significantly related to low histological grade, ER-positive status and PR-positive status and was also associated, although not significantly, to small tumor size (<2 cm)." (PMID 23241075, 2012). "In the LuCaP 86.2 tumor, beside a weak 110 KDa band, N-terminal AR antibody also identified an 80 KDa AR isoform that corresponded to the predicted size of the C-terminal truncated AR splice variant-ARv567es while C-terminal AR antibody did not." (PMID 22114732, 2011). "Besides, androgen receptor (AR) expression was detected heterogeneously during tumor progression." (PMID 21241512, 2011). "Increased oxidative stress has been shown to promote tumor proliferation and survival through dysregulation of redox sensitive pathways.Here, we discuss the possible role of Nrf1 and Nrf2 in regulating the expression of antioxidant enzymes that can modulate AR signaling in PCa." (PMID 24281119, 2010). "Increased levels of the AR protein itself, whether achieved through gene amplification or by other pathways, seems to be the most important (or at least most common) pathway to HR tumor recurrence in the majority of tumors." (PMID 20406442, 2010). "Therefore, in a relatively short temporal window overall cancer incidence may be reduced, but a minority of patients will cross the threshold for increased AR expression and experience a high-grade tumor." (PMID 20406442, 2010). "Likewise there was a significant up-regulation of TSP1 protein coupled with a down-regulation of HIF1α protein, androgen receptor protein (AR), and glucose transporter-1 protein (i.e. down stream target of HIF1α) within tasquinimod treated tumor tissues excised and prepared on day 28 (p < 0.05)." (PMID 20470445, 2010). "Interestingly, the sequence specificity of siRNA allowed here discriminating in vivo the closely related mouse and human AR mRNAs: treatment with hAR-siRNA silenced AR in tumor cells and inhibited the tumor growth while preserving AR expression in mouse prostate and testes." (PMID 17925854, 2007). "Additionally, PSA expression was lower in the cyclin D1-positive tumours, indicating that cyclin D1 status may affect expression of serum markers that are dependent on AR activity." (PMID 17375037, 2007). "Indeed, activation of both the progesterone receptor (PR) and the androgen receptor (AR) have been shown to reprogram the ER cistrome: reinstalling a gene-expression program of favorable outcome and repressing ER-regulated cell cycle genes, whilst upregulating known tumor suppressors." (PMID 41261233, 2026). "Our results from healthy tissue (GTEx) and tumor (TCGA) analysis demonstrated a significant negative correlation between AR activity and the three IFNγ-associated signature scores in normal tissue and tumors, suggesting conserved AR-regulated biology irrespective of malignancy status." (PMID 41486951, 2026). "Preclinical studies have demonstrated that AR suppression, tumor hypoxia and tumor-microenvironment interactions promote MET upregulation, supporting AR-independent growth and epithelial-to-mesenchymal transition." (PMID 42122259, 2026). "Immunohistochemical staining demonstrated that the tumor cells were positive for CD34, desmin, androgen receptor, and progesterone receptor." (PMID 41529035, 2026). "In the context of cancer and the tumor microenvironment (TME), AR is expressed in various immune cell types, including neutrophils, macrophages, T cells, and B cells, and contributes to the regulation of both innate and adaptive immune responses." (PMID 41486951, 2026).
tumor (continued). "In AR-positive cells, CREB5 overexpression promoted cell colony growth with tumorigenic properties and increased tumor size in vivo." (PMID 41954995, 2026). "Other than their canonical function of catalyzing different histone PTM reactions, they can function as AR transcriptional coactivators and promote DNA damage repair, regulate PI3K/AKT, WNT signaling, and enhance tumor angiogenesis." (PMID 41601922, 2026). "Immunohistochemical staining showed that the tumor cells were positive for BerEp4, GATA‐3, AE1/AE3, CAM5.2, ER (70%), AR (10%), PR (10%), and ki67 (10%)." (PMID 41239938, 2026). "Superior MTA1-mediated anticancer effects of Gnetin C also included a downregulation of oncogenic/tumor-promoting ETS2, pAkt/Akt, Cyclin D1, p-mTOR/pS6K/p4EBP1 and AR signaling." (PMID 40077738, 2025). "Conversely, elevated levels of MYC diminishes the AR transcriptional program in pre-clinical models and CRPC tumours, at least in part by disrupting transcriptional pause release at AR target genes." (PMID 40163908, 2025). "This form of "promiscuous" AR activation undermines the efficacy of ADT, contributing to the persistence of tumor growth." (PMID 41235005, 2025). "HCCLM3 cells express both AR-FL and AR-SV, representative of the AR tumor status in most HCC patients, while SNU475 cells solely express AR-SV due to a genomic deletion in the ligand-binding domain (LBD)." (PMID 40805231, 2025). "UTY encodes a histone demethylase that is capable of epigenetically regulating AR (androgen receptor) target genes such as PTEN, thereby potentially promoting tumor cell proliferation." (PMID 40299503, 2025). "Of note, both SAL and AR antagonists induce cellular senescence in CSPC and CRPC in adherent PCa cell lines, in PCa tumor spheroids and in mouse xenografts." (PMID 41264145, 2025). "AR-dependent mechanisms are central to the pathogenesis and progression of CRPC, allowing tumor cells to maintain growth and survival despite systemic androgen deprivation." (PMID 41235005, 2025). "Immunohistochemistry showed strong membranous positivity of the tumour cells with HER2 and androgen receptor." (PMID 41458668, 2025). "These sEVs are internalized by HCC cells to downregulate androgen receptor (AR) expression, activating the AR/PHLPP/p-AKT/β-catenin signaling axis and promoting tumor progression." (PMID 40703510, 2025). "Tumor tissues were assessed using immunohistochemistry for ER, PR, HER2, AR, and Ki67, along with TAN evaluation using hematoxylin and eosin staining." (PMID 40734715, 2025). "To gain a better understanding of the regulatory effects on several tumor-related signaling pathways, we studied the protein expression of MED12, AR, AR-V7 and c-Myc via Western hybridization." (PMID 40133664, 2025). "Earlier, we reported proteasomal degradation of androgen receptor (AR)/AR‐Vs and Mnk1/2 as the primary mechanisms of action of VNPP433‐3β in inhibiting PCa cell proliferation and tumor growth." (PMID 40007440, 2025). "Spatial biomarker profiling has been accomplished using QD-labeled nanoarrays and imaging assays for proteins like androgen receptor (AR), E-cadherin, and RANKL, further supporting multiplexed diagnostics and tumor microenvironment analyses." (PMID 40801702, 2025). "Nonetheless, the complexity of mPCa necessitates combination strategies, such as pairing AR inhibition with PI3K/AKT blockade or PARP inhibitors, to inhibit tumor plasticity." (PMID 40427518, 2025). "The epithelium still retained the biphasic morphology of the adjacent canalicular tumor with CK7- and AR-immunopositivity of the luminal cells." (PMID 40033554, 2025). "AR signaling mediates CD8+ T cell exhaustion, contributing to sex differences in tumor aggressiveness, with male-biased expression driven by androgens impacting antitumor immunity." (PMID 40458476, 2025).
tumor (continued). "Furthermore, functional enrichment analysis suggests that hsa-miR-6715b-3p may regulate key pathways involved in PCa progression, particularly the MAPK and autophagy pathways, which are known to contribute to androgen receptor signaling, therapy resistance, and tumor cell survival." (PMID 40044915, 2025). "Numerous studies have shown that CHIP acts as a tumor suppressor in CRPC by mediating the ubiquitination and degradation of oncogenic TFs such as AR/AR-V7 and HIF1α22,42–44." (PMID 41028522, 2025). "Prior work in BC preclinical models indicated that metastatic tumor cells are reliant on OXPHOS and that AR is elevated in anchorage-independent BC cells." (PMID 41216931, 2025). "In this study, we evaluated the expression levels of HIC1, AR, IRS2, and EMT‐related proteins, as well as the activation status of the PI3K/AKT pathway in PCa mouse tumor tissue using RT‐qPCR and Western blot experiments." (PMID 41050263, 2025). "Evidence has demonstrated that AR, the client protein of the HSP27, is frequently overexpressed in GBM and contributes to tumor progression." (PMID 40572374, 2025). "Despite androgen deprivation, AR remains active in castration-resistant prostate cancer (CRPC), sustaining tumor growth." (PMID 41440174, 2025). "Previous research has reported that AMPK activation can inhibit androgen receptor (AR) transcriptional activity, which is crucial for PCa progression, thus indicating AMPK as a tumour suppressor in PCa." (PMID 39973042, 2025). "Reactivation of androgen receptor (AR) signaling remains the principal driver of CRPC cell survival and tumor progression even under castrated levels of serum androgen." (PMID 41247636, 2025). "Androgen deprivation therapy (ADT) or AR antagonists can downregulate TMPRSS2 expression, potentially reducing both tumor growth and SARS‐CoV‐2 infectivity." (PMID 40145441, 2025). "We then developed an AR-positive, ENZ-resistant PDX subline from LuCaP35 CRPC PDX model through consecutive treatments of the tumor-carrying mice with 20 mg/kg ENZ (p.o.)." (PMID 41231955, 2025). "Mechanistically, CCL5 binds to the CCR5 receptor on tumor cell surfaces, activating the downstream AKT signaling pathway, which cooperatively promotes AR and PD-L1 upregulation, ultimately driving CRPC progression and therapy resistance." (PMID 41154598, 2025). "The combination of AR and JAK2/STAT1 inhibition resulted in a significant reduction in tumor growth, which was attributed to the diminished capacity for DNA damage repair and the increased propensity for apoptosis." (PMID 40001606, 2025). "In fact, androgen receptor (AR) inhibitors strongly reduce GPX4 expression, demonstrating that AR promotes and drives GPX4 expression in LAR subtype of TNBC tumor." (PMID 41339932, 2025). "The findings reveal that EVO can markedly enhance the expression of the androgen receptor (AR) in OSCC cells, inducing cellular senescence and thereby inhibiting tumor progression." (PMID 40729027, 2025). "HER2-high/AR-low cells present before therapy resisted ADT yet were sensitive to HER2 inhibitors; combining HER2 inhibitors with enzalutamide increased tumor cell killing." (PMID 40906535, 2025). "The compound decreased transcriptional activity of AR and downstream prostate‐specific antigen (PSA) expression in LNCaP cells, which led to inhibited proliferation of tumor cells." (PMID 41179371, 2025). "BWA-522 exhibited AR degradation with a DC50 value of 3.5 μM in LNCaP cells and demonstrated effective tumor growth inhibition following oral administration." (PMID 40507351, 2025). "Sex-specific differences in anti-tumor immune responses in mice have been attributed, at least in part, to AR-mediated epigenetic remodeling of CD8+ T cells leading to lower reactivity and stemness in the tumor environment." (PMID 40406098, 2025).
tumor (continued). "Using the novel AR-antagonist compound 28 (C28), that inhibits also those AR mutants mediating therapy resistance, represses growth including CRPC tumor spheroids and mouse xenografted tumors." (PMID 40368177, 2025). "AR expression was found in both normal liver tissue and HCC, with an overall higher expression in tumor regions." (PMID 41228208, 2025). "As a result, research efforts in PTEN-altered PC have concentrated on simultaneously targeting both the AR and PI3K/AKT pathways to restrict tumor growth and overcome resistance." (PMID 39796175, 2025). "The second-generation androgen receptor pathway inhibitor (ARPI) apalutamide is a widely utilized therapeutic agent in this context, reducing tumor volume by suppressing tumor cell proliferation and enhancing apoptosis." (PMID 41353166, 2025). "NRG1 secreted by CAFs acts in a paracrine manner to sustain tumor growth and confer resistance to both enzalutamide and ADT through AR-independent mechanisms, contributing to castration resistance." (PMID 41228234, 2025). "AR blockade, otherwise known as ADT (anti-androgen therapy), has been demonstrated to induce tumor regression in up to 80% of PCa patients." (PMID 41228300, 2025). "Reciprocal feedback between these pathways allows tumor cells to escape therapy as AR inhibition can activate AKT signaling via increased phosphorylation, while AKT blockade can stimulate AR signaling, promoting cancer progression." (PMID 41228234, 2025). "Moreover, the activation and expression of AR can promote the invasion, dissemination, growth, and advancement of cancer cells through different pathways, such as inhibiting the release of immune factors, boosting tumor immune escape, stimulating angiogenesis, and triggering the EMT process." (PMID 39927164, 2025). "Additional immunohistochemical examinations of the resected tumor tissue showed positive expression of AE1/AE3, PSAP, PSMA and partially weakly positive for PSA, as well as nuclear positivity for AR." (PMID 40181402, 2025). "While the overexpression of FOXA1 and HOXB13 pushes AR cistrome to a more tumor-like profile, pioneering activity of GATA2 allows AR to bind to enhancers of metastasis and treatment resistance associated genes, thereby contributing to PCa progression." (PMID 40833121, 2025). "As a result, androgen-deprivation therapy, which inhibits AR signaling, has long been a cornerstone of initial treatment, leading to decreased PSA levels and tumor volume." (PMID 40361461, 2025). "Blocking AR enhances CD8 T cell function and sensitizes tumor-bearing hosts to effective immune checkpoint blockade." (PMID 40438106, 2025). "Preclinical studies demonstrate that enzalutamide, a second-generation AR antagonist, increases CD8+ T-cell infiltration in AR-positive TNBC tumor tissues and enhances the effectiveness of immune checkpoint inhibitors." (PMID 41584838, 2025). "Positive values of AR/ESR1 and AR/PGR ratios were also observed in the ER-negative (ER-) cell line MDA-MB453, as well as in tumor tissue from ER- BC patients." (PMID 40593140, 2025). "For example, it has been shown that AR can directly regulate acyl-CoA synthetase medium-chain family members 1 and 3 (ACSM1 and ACSM3), both of which are up-regulated in tumor tissues." (PMID 41281744, 2025). "To further investigate the impact of HIC1/AR/IRS2 on the proliferation and metastasis of PCa cells, we conducted immunohistochemical analysis on PCa xenograft tumor slices." (PMID 41050263, 2025). "In vivo studies using ADM-21, a miR-21 inhibitor, have shown reduced tumor growth and PTEN restoration in xenograft models, underscoring the therapeutic potential of targeting the miR-21/PTEN/AR axis." (PMID 40806474, 2025).